FASN (fatty acid synthase)
Diseases named in the same sentence as FASN in open-access papers (continued):
Sharing a sentence is not in itself a finding about the gene and the disease.
cancer (continued). "FASN is overexpressed in various cancers, including epithelial ovarian carcinoma (EOC)." (PMID 29642900, 2018). "However, the role of upregulated FASN in cancer cells and the detailed mechanisms of tumor cells killing by an inhibitor of FASN are still not fully understood." (PMID 30619288, 2018). "Research shows that anti-cancer function can occur by inhibiting the expression of the lipogenic enzyme FASN in Human Epidermal Growth Factor Receptor2 (HER2)-overexpressing breast carcinoma cells, and thus offers a previously unrecognized mechanism for EVOO-related cancer preventive effects." (PMID 30151359, 2018). "Thus, both progenitor and cancer cells rely on FASN activity for proliferation, and FASN inhibitors are currently under study as potential anticancer therapies." (PMID 29434029, 2018). "FASN is an enzyme overexpressed in many cancer types that plays a key role in tumorigenesis." (PMID 30153655, 2018). "Our results reinforce the theory that FASN could be an important target to manipulate the fatty acid and lipid metabolism in cancer and therefore control cancer cell behaviour." (PMID 30559929, 2018). "Likewise, suppression of FASN expression and activity by cerulenin, C75, orlistat, or triclosan demonstrates apoptosis induction in many cancer cell lines." (PMID 29588626, 2018). "Interestingly, high-throughput analysis of Cancer Genome Atlas data identified distinct targets, including Fatty acid synthase FASN and Matrix Metallopeptidase 1 MMP1 as novel, promising combination therapy partners." (PMID 30283446, 2018). "Thus, one of the molecular pathways by which osthol performs its protective action against cancer progression is its potent inhibitory effect on FASN." (PMID 29301373, 2018). "In addition to tumor promoting effect on cancer cells, FASN and Cav-1 have been reported to protect cancer cells from chemotherapy by inducing drug resistance." (PMID 29568521, 2018). "In cancer cells, expression of FASN is modulated by sterol regulatory element-binding protein 1c (SREBP1) and proto-oncogene FBI-I (Pokemon) via dysregulated mitogen activated protein kinase or phosphoinositide 3-kinase/AKT pathways under hormonal or nutritional regulation." (PMID 29996946, 2018). "Several FASN inhibitors display anti-tumor activity in preclinical cancer models." (PMID 29907133, 2018). "According to HITS‐CLIP experiment evidence from TarBase, both miR‐330‐5p and miR‐326 may directly interact with fatty acid synthase (FASN) which emerges as an oncogene in various cancers." (PMID 29722168, 2018). "Decreased activity of fatty acid synthase and lipoprotein lipase was shown in adipose tissue of cancer patients and adipogenesis, a process essential to form mature adipocytes, is impaired in experimental models of cancer cachexia with reduced expression of adipogenic transcription factors." (PMID 30061533, 2018). "The observation that decreased lipogenesis might stimulate cell invasion and metastases raises significant attention in considering FASN targeting and/or other lipogenic enzymes as potential therapeutic target for cancer treatment." (PMID 28352611, 2017). "In contrast, FASN is highly expressed in many cancer and precancerous lesions." (PMID 28421159, 2017). "While oncogenic functions of FASN, DAG, PKC, PIPs, and PI3K-mTORC1 have already been demonstrated, the influence of FASN(-inhibitors) on phosphatidylinositol (PI) metabolism and signaling in cancer is still unknown." (PMID 28086243, 2017). "Moreover, down-regulation of FASN and inhibition of FASN activity offer a promising therapeutic anticancer effect by inducing tumor cell-cycle arrest and cancer cell death." (PMID 28786914, 2017). "Recently, fatty acid synthase (FASN) has been considered as a potential target to treat cancer." (PMID 28212342, 2017).
cancer (continued). "We finally validated our predictions by demonstrating the functional relationships among the expression of these genes and FASN, liver fat, and cell growth, by using human cancer cell lines, mouse liver samples (four different mouse studies), and human hepatocytes." (PMID 28827398, 2017). "Implications of FASN in tumor growth in various cancers have been suggested." (PMID 27765901, 2016). "Also, downregulation of FASN in cancer has contributed to chemopreventive action of celecoxib, a drug for the COX-2 pathway." (PMID 27270654, 2016). "Interestingly, we highlighted evidences that CAV1 interacts with known mediators of altered metabolism, e.g. LDHA, PKM2 and FASN, which are currently being studied as cancer drug targets." (PMID 27852311, 2016). "In preclinical studies, it was shown that the FASN inhibitor was effective in inducing apoptosis of several tumor cell lines and in reducing tumor growth in several cancer xenograft models, but its effect in inhibiting EMT/metastasis has not been extensively studied in animal models." (PMID 27765901, 2016). "FASN modulates Cav-1-dependent signaling pathways and controls proliferation of cancer cells." (PMID 27980732, 2016). "Moreover, cancer cells can accelerate the synthesis of Ac-CoA (designated as larger font size), a substrate of FASN via reductive carboxylation in mitochondria under conditions of hypoxia." (PMID 27589734, 2016). "SREBPs mediate the activation of multiple genes by binding to sterol regulatory elements within the regulatory regions of genes such as FASN, which encodes fatty acid synthase (FASN), and SCD, which encodes stearoyl CoA desaturase-1 (SCD-1) and is involved in LD formation in cancer cells." (PMID 27589734, 2016). "C-75, a FASN inhibitor, has been studied as a novel therapeutic agent in PCa cells; recent reports have shown that FASN inhibition leads to malonyl-CoA accumulation, with toxic effects in cancer cells." (PMID 27331874, 2016). "The fatty acid synthase is overexpressed in various cancers and could catalyze the de novo synthesis of fatty acids from acetyl-CoA." (PMID 26754531, 2016). "In contrast, FASN is highly expressed in many cancers and precancerous lesions." (PMID 27223259, 2016). "Despite its promise as a target for anti-cancer therapeutics, the mechanism by which FASN is dysregulated in cancer is unknown." (PMID 27223259, 2016). "Since the end product of FASN and common intermediate in all de novo fatty acid synthesis is palmitate, we asked if the decrease in palmitate production was responsible for the impaired cell proliferation in cancer cells with BRG1 knockdown." (PMID 27223259, 2016). "Reduction in FASN enzyme activity by chemical inhibitors including orlistat, cerulenin (unapproved for use in humans) and triclosan have been reported to remarkably decrease progression in various cancer cell types." (PMID 27270654, 2016). "Furthermore, genes encoding lipogenic enzymes such as FASN and SCD-1 are upregulated in cancer cells in response to hypoxia." (PMID 27589734, 2016). "The fact that sole correction of exacerbated lipogenesis can stably reprogram cancer cells back to normal-like tissue architectures might open a new avenue to chronically restrain BC progression by using FASN-based differentiation therapies." (PMID 27223424, 2016). "FASN is overexpressed in cancers and plays an oncogenic role in cancer development and progression." (PMID 27713175, 2016). "Accumulating evidence shows elevated expression/activity of FASN in many types of cancers." (PMID 27765901, 2016). "FASN contributes to mammary oncogenesis and serves as a bona fide target in cancer therapies." (PMID 27713175, 2016). "Similarly, fatty acid synthase (FASN), the key enzyme of de novo lipogenesis, is found to be highly active in a large variety of cancers, and its up-regulation is associated with chemotherapeutic drug resistance." (PMID 25669981, 2015).
cancer (continued). "Knowing that EGFR's palmitoylation plays a critical role in its function, we sought to test whether inhibition of FASN or PATs activity can increase the sensitivity of cancer cells to EGFR tyrosine kinase inhibitors (EGFR TKI)." (PMID 26378037, 2015). "In addition to oxidative stress, fly homologs of metabolic genes that fuel human cancer growth are elevated, including fatty acid synthase (FASN) which facilitates de novo lipogenesis, and LDH which promotes aerobic glycolysis in the Warburg effect." (PMID 25719210, 2015). "In the present study, we test the hypothesis that overexpression of FASN promotes a switch in metabolic pathways that drives cellular bioenergetics along routes that support cancer cell survival during CRC progression." (PMID 25970773, 2015). "It was proposed that certain signaling pathways involved in cell apoptosis were closely associated with the inhibition of FASN, which helps to explain why FASN inhibitors may potentially be used to treat cancer." (PMID 25947066, 2015). "Finally, tumors that express low levels of Mov10 express higher levels of FASN, providing correlative evidence for Mov10-regulated lipid metabolism in cancer." (PMID 26029828, 2015). "For those reasons, FASN has become as an attractive target for cancer therapy in last 15 years." (PMID 25433947, 2015). "Overexpression of FASN has been shown to promote cancer growth and metastasis." (PMID 25970773, 2015). "Targeted therapies using FASN inhibitors, such as C75, decrease the cancer cell proliferation and tumor growth and may offer new therapeutic opportunities for cancer." (PMID 26002551, 2015). "It is necessary to discover additional FASN inhibitors that may be applied practically in the treatment of cancer." (PMID 25009654, 2014). "However, the side effects of existing FASN inhibitors have so far precluded their clinical use in cancer." (PMID 25502566, 2014). "Therefore, targeting fatty acid synthase can be an important strategy for cancer prevention and treatment." (PMID 24778702, 2014). "Other FASN inhibitors that can potentially be used as cancer treatment drugs have been identified, such as Orlistat (1-(3-hexyl-4-oxooxetan-2-yl) tridecan-2-yl 2-formamido-4-methylpentanoate), a drug designed to treat obesity and marketed as a prescription in most countries." (PMID 24778702, 2014). "The authors also propose a probable model by which FASN regulates the transcription of E-cadherin/N-cadherin and by which FASN-mediated EMT provides a mechanism of escape for the primary cancer cell to disseminate, ensuring cell survival in the peritoneal cavity." (PMID 24979135, 2014). "Research has also shown that, through the inhibition of FASN activity or the reduction of its expression, cancer growth could be effectively reduced or apoptosis could be induced." (PMID 24778702, 2014). "Thus, the high level of FASN expression in HepG2 cells is essential for cancer cell proliferation and responsiveness to capsaicin or other FASN inhibitors." (PMID 25255125, 2014). "In the current study, similar to reported FASN inhibitors, such as C75 and cerulenin, quercetin could induce apoptosis in cancer cells." (PMID 25009654, 2014). "It was proposed that certain signaling pathways involved in cell apoptosis were closely associated with the inhibition of FASN, which may help to explain why FASN inhibitors may potentially be used to treat cancer." (PMID 25009654, 2014). "In addition to cancer cells, high expression of FASN has been reported in lipogenic tissue, such as the liver." (PMID 25255125, 2014). "In short, the inhibition of FASN can effectively and widely inhibit the DNA replication of cancer cells and delay the S phase in the cell cycle, demonstrating that the pathway of fatty acid synthesis and DNA synthesis activity is related to the growth of cancer cells." (PMID 24778702, 2014).
cancer (continued). "However, there is still the question of which mechanism mediates the inhibitory effect of capsaicin on suppression of FASN expression and its activity on fatty acid synthesis in cancer cells." (PMID 25255125, 2014). "In contrast to most normal tissues, a variety of human cancers overexpress FASN." (PMID 24964211, 2014). "Previous studies have suggested that the mechanism of apoptosis through inhibiting FASN could be explained by the accumulation of malonyl-CoA, which was likely to trigger cancer cell death and induce apoptosis." (PMID 25009654, 2014). "The study supports that FASN is a novel target for cancer therapy." (PMID 24778702, 2014). "Indeed, overexpression and increased activity of FASN, a key enzyme responsible for the terminal step in FA synthesis, represents one of the most frequent phenotypic alterations in cancer cells." (PMID 24497570, 2014). "However, in cancer cells and pre-neoplastic lesions, FASN expression has been frequently found to be upregulated." (PMID 23725225, 2013). "FASN is critical to sustain the biological features of cancer cells." (PMID 23599729, 2013). "Cancer cells produce more FASN, likely because it promotes cell proliferation, which could lead to higher incorporation into the exosomes." (PMID 24391718, 2013). "Inhibition of FASN may be responsible for cancer cell death as FASN inhibition introduces changes in the synthesis of membrane phospholipids." (PMID 23292678, 2013). "FASN expression is upregulated in a number of cancers including ovarian, breast, and prostate so the discovery that orlistat was a novel inhibitor of FASN triggered numerous studies into the efficacy of orlistat as a therapeutic agent for cancer." (PMID 23573093, 2013). "Moreover, it was reported that t10,c12-CLA was able to down-regulate Fatty Acid Synthase or antioxidant defence systems in different human cancer cells." (PMID 24260504, 2013). "Findings of the present study demontstrated that quercetin was able to inhibit cell proliferation and may present a means to block uncontrolled growth of cancer cells expressing increased levels of fatty acid synthase." (PMID 23292678, 2013). "All these findings suggest that FASN may be used for diagnosis, prognosis, early intervention, and treatment of various human cancers." (PMID 23725225, 2013). "In light of the evidence linking FA synthesis to oncogene signalling, it is possible that activation of SREBP and FASN could also stimulate processes involved in endothelial cell recruitment and induction of tumour vasculature by the cancer cells." (PMID 24203995, 2013). "Moreover, the upregulation of FASN expression is an early event in cancer development, it is more pronounced in advanced tumors, and correlates with a poor prognosis." (PMID 23725225, 2013). "Likewise, pharmacological inhibitors of fatty acid synthase (FASN), a metabolic enzyme highly expressed in PC, induce apoptosis in prostate and other cancer cells." (PMID 23213321, 2012). "Thus the fatty acid synthesis pathway has been an attractive cancer target for some time, and primary attention has focused on fatty acid synthase, which marks the point of production of long-chain fatty acids." (PMID 22457791, 2012). "Moreover, upregulation of FASN gives cancer cells a growth and survival advantage by blocking apoptosis under hypoxia, a common condition in solid tumors and tumor effusions." (PMID 20508725, 2010). "The mechanism underlying upregulation of FASN in human cancer is not clear and it likely involves multiple pathways." (PMID 20508725, 2010). "Moreover, in normal breast tissues, again, a striking spatial concordance in the expression of Mb and FASN was seen (left), which was also partially retained in cancer (right)." (PMID 20531416, 2010). "Interference of these pathways could also be involved in the FASN inhibition-induced selective cancer cytotoxicity." (PMID 19352381, 2009).
cancer (continued). "In addition to the essential role of FASN in cancer cell growth and survival, it is involved in other phases of cancer development." (PMID 19352381, 2009). "Among them, FASN overexpression is observed in a wide variety of human cancers." (PMID 19352381, 2009). "As it has recently been suggested that p63 functions in maintaining the proliferative potential of epidermal stem cells, it will be critical to establish whether the same genetic program plays a role in cancer stem cells and whether FASN is involved." (PMID 19517019, 2009). "Considering the fact that tumour microenvironment stresses are strong inducers of the endoplasmic reticulum stress, the FASN inhibitors could show selective and enhanced cytotoxicity to cancer cells under the tumour microenvironment conditions." (PMID 19352381, 2009). "Polymorphisms of FASN gene are the other factors that could affect the effectiveness of FASN-targeting agents on cancer." (PMID 19352381, 2009). "In line with this hypothesis, inhibition of the FASN pathway by either FASN inhibitors including C75 or Cerulenin, or by silencing FASN expression with RNAi result in G1 arrest and/or induction of apoptosis in various cancers cells." (PMID 19517019, 2009). "Although the precise mechanisms of FASN inhibition-induced cell death in cancer cells still remain unknown, several possibilities have been proposed." (PMID 19352381, 2009). "Hypoxia and low pH stress induce the FASN expression in cancer cells." (PMID 19352381, 2009). "This suggests that the specificity of FASN inhibitors could be a critical key for successful molecular target therapy of cancer." (PMID 19352381, 2009). "However, cancer cells, especially of the breast, prostate, colon, ovary, endometrium, and thyroid origin, express very high levels of FASN and this up-regulation is under the control of aberrant MAPK and PI-3K-Akt signaling." (PMID 18523653, 2008). "Most of these cancer types express very high levels of FASN." (PMID 18523653, 2008). "Theoretically, a combinational use of these genotoxic drugs or radiotherapy with inhibitors for FASN might be beneficial, at least for pre-cancer cells when the DNA damage response pathway is still intact." (PMID 18523653, 2008). "However, cancer cells could adapt to FASN inhibition by switching from de novo FA synthesis to FA uptake." (PMID 40814339, 2025). "Therefore, FASN is involved in cell proliferation and contributes to many hallmarks of cancers." (PMID 40684943, 2025). "These collective findings establish the dual role of FASN in suppressing apoptosis and promoting angiogenesis across multiple cancer types, thereby substantiating our hypothesis that FASN acts as the mechanistic executor through which the circHIPK3/ALYREF axis drives oncogenic effects in GBC." (PMID 40466438, 2025). "Other studies also showed that inhibiting FASN could sensitize cancer cells to RT." (PMID 40102409, 2025). "Moreover, α-linolenic acid (ALA), an omega-3 fatty acid, induces apoptosis and inhibits invasion, metastasis and angiogenesis, and arrests the cell cycle in human BC cells by inhibiting fatty acid synthase (FASN), which is usually overexpressed in various cancers." (PMID 39456858, 2024). "Interestingly, yarrow-Sep inhibited key lipid metabolic targets in CRC cells extensively shown to be implicated in cancer dissemination and prognosis —SREBF1, FASN, ABCA1 and HMGCR— and epithelial to mesenchymal targets—CDH1, ATP1B1, CDH2 and Vimentin—augmenting cell adhesion." (PMID 38576446, 2024). "In addition, another study showed that MT19c specifically targets the metabolic pathways of cancer cells, particularly by inhibiting fatty acid synthase (FASN) functions and disrupting de novo lipogenesis, which is a characteristic feature of cancer cell metabolism in both in vitro and in vivo." (PMID 39077471, 2024).